TSLP (thymic stromal lymphopoietin)
Diseases named in the same sentence as TSLP in open-access papers (continued):
Sharing a sentence is not in itself a finding about the gene and the disease.
pancreatic cancer (29 papers, 2014 to 2025). "Although both ILC2s and TSLP are individually implicated in pancreatic cancer immunology, a direct link between TSLP and ILC2s has yet to be demonstrated but would appear likely." (PMID 40899118, 2025). "TSLP is upregulated in pancreatic tumours and is associated with a Th2‐dominant immune microenvironment, which correlates with worse patient outcomes." (PMID 40899118, 2025). "A recent study identified IL-1α and IL-1β released by pancreatic cancer cells and tumor-associated macrophages as relevant stimuli for TSLP release from CAFs." (PMID 40873585, 2025). "TSLP production by cancer-associated fibroblasts in pancreatic cancer induces Th2 type inflammation and is associated with poorer patient outcome." (PMID 33540635, 2021). "In pancreatic cancer, TSLP is associated with a reduced survival of patients, in which TSLP is produced by tumour-derived IL-1β-activated cancer-associated fibroblasts (CAFs) and favours Th2 cell polarisation via myeloid DC." (PMID 33652749, 2021). "De Monte and collaborators have demonstrated in human pancreatic cancer that TSLP drives the differentiation of TH2 cells and is associated with a worse prognosis." (PMID 34440780, 2021). "Thymic stromal lymphopoietin (TSLP) is a cytokine associated with type 2 immunity and is also associated with the progression of various cancers, including BC, pancreatic cancer, gastric cancer, cervical cancer, and myeloma." (PMID 32841536, 2020). "Recently, a study using a non-orthotopic transplantable PDAC mouse model with high levels of systemic TSLP reported impaired pancreatic cancer development associated with tumor infiltration by Th2 cells." (PMID 30760333, 2019). "In some cancers, including breast 72, gastric 73 and pancreatic cancer 74, 75, Th2 cells and associated cytokines [IL‐4, IL‐13, Thymic stromal lymphopoietin (TSLP)] contribute to tumour progression." (PMID 28032353, 2017). "However, due to the different functions exerted by the two TSLP isoforms, in pancreatic cancer where both isoforms can be expressed, targeting cytokines and molecules implicated in the induction of the inflammatory long TSLP isoform would be preferable." (PMID 30760333, 2019). "Moreover, in pancreatic cancer, the secretion of thymic stromal lymphopoietin (TSLP) by CAFs has been associated with a TH2 cell polarization through myeloid DC conditioning." (PMID 29545811, 2018). "In pancreatic cancer, CAFs have been found to secrete thymic stromal lymphopoietin (TSLP) following activation by tumor-derived TNF-α and IL-1β." (PMID 40453074, 2025). "Protti and collaborators first demonstrated that human pancreatic cancer [pancreatic ductal adenocarcinoma (PDAC)]-derived TNF-α and IL-1 induced the release of TSLP from cancer-associated fibroblasts (CAFs)." (PMID 40873585, 2025). "TNF and IL-1 stimulate CAF in human pancreatic tumors to produce thymic stromal lymphopoietin (TSLP), which indirectly promotes Th2 cells by acting on dendritic cells." (PMID 37007004, 2023). "The effects of TSLP on tumor microenvironments of tumor including lung cancer, breast cancer, and pancreatic cancer had been carried out step by step in previous studies." (PMID 32351590, 2020). "The following studies identified a complex crosstalk in the tumor microenvironment and tumor-draining LNs (TDLNs) relevant to the establishment of TSLP-dependent Th2-type inflammation in pancreatic cancer." (PMID 33042121, 2020). "Recent studies show that pancreatic tumor production of IL-1 alpha and beta is a stimulant for TSLP secretion by CAFs." (PMID 32466266, 2020). "Treatment of immunodeficient mice orthotopically injected with human IL-1 positive pancreatic cancer cells plus CAFs using the IL-1R antagonist anakinra significantly reduced TSLP expression in the tumor." (PMID 30760333, 2019).
pancreatic cancer (continued). "Human data from pancreatic cancer patients indicated that DCs with features of TSLP-treated DCs and Th2-attracting chemokines were present in pancreatic tumors, and the Th2/Th1 ratio in pancreatic tumors was an independent marker of poor survival." (PMID 31428105, 2019). "We show in vitro that IL-1α and IL-1β released by pancreatic cancer cells and tumor cell-conditioned macrophages are crucial for TSLP secretion by CAFs." (PMID 30760333, 2019). "Our findings indicate that tumor released IL-1α and IL-1β and ASC are key regulators of TSLP secretion by CAFs and their targeting should ultimately dampen Th2 inflammation and improve overall survival in pancreatic cancer." (PMID 30760333, 2019). "In particular, in the presence of systemic TSLP, spontaneous pancreatic tumors transferred to K14-TSLPtg mice grew less than those in WT mice, with a significant increase in GATA3+ Th2 infiltrating cell numbers." (PMID 30214685, 2018). "Since TSLP is a secreted protein, and is highly expressed in pancreatic tumor tissues, plasma TSLP levels were measured in a group of locally-advanced/metastatic PDAC patients, and its potential clinical significance was assessed." (PMID 30214685, 2018). "Elevated TSLP expression has been reported in some types of tumor, such as breast and pancreatic tumor, which promotes tumor growth and positively correlates with the presence of metastasis and negatively with prognosis." (PMID 26919238, 2016). "This is in contrast to the reported ability of TSLP to shrink tumours in Notch-deficient skin, but in agreement with the potent tumorigenic effect of TSLP in breast and pancreatic cancers." (PMID 24843010, 2014). "IL-1α and IL-1β from pancreatic cancer cells released TSLP from CAFs." (PMID 40873585, 2025). "As a potential solution, blocking TSLP production by CAFs could help improve the prognosis of pancreatic cancer." (PMID 40453074, 2025). "Similarly, in pancreatic cancer, CAFs facilitate a shift toward a Th2 immune response through the secretion of TSLP in response to TNF-α and IL-1β, which polarizes DCs toward an immunosuppressive phenotype." (PMID 40453074, 2025). "Importantly, TSLP-activated WT CD4+ Th2 cells suppressed P48-Cre LSL-KrasG12D p53f/f pancreatic tumor growth compared with TslprKO CD4+ T cells in Tslptg TslprKO recipient mice." (PMID 35657353, 2022). "TSLP overexpression was found in tumor tissues of lung cancer and pancreatic cancer." (PMID 32351590, 2020). "The thymic stromal lymphopoietin (TSLP), a key cytokine for development of Th2 immunity, is produced by cancer associated fibroblasts (CAFs) in pancreatic cancer where predominant tumor infiltrating Th2 over Th1 cells correlates with reduced patients’ survival." (PMID 30760333, 2019). "A study on pancreatic cancer, in which a Th2 (GATA3+) cellular infiltrate is predominant, identified a central role for cancer-associated fibroblasts (CAFs) in conditioning DCs with Th2-polarizing capability, via TSLP secretion." (PMID 30214685, 2018). "TSLP plays a significant role in the tumor microenvironment leading to tumor progression and promotion of angiogenesis and metastasis in both solid tumors, such as cervical, ovarian, and pancreatic cancer; and liquid tumors, such as lymphoma and acute lymphoblastic leukemia." (PMID 35558081, 2022). "Recent studies have indicated that TSLP overexpression may promote the survival, growth, and metastasis of many solid tumors with a Th2-biased immune response, including cervical, breast and pancreatic cancer, and cutaneous T-cell lymphoma." (PMID 31023965, 2019). "In this model, pancreatic tumor cells release TNF-α and IL-1β proinflammatory cytokines, which had been previously reported, stimulating CAFs to secrete TSLP." (PMID 40453074, 2025). "Interplay between CAFs and DCs has also been shown to affect the ability of DCs to induce the differentiation of T cells into a Th2 phenotype in pancreatic cancer, via CAF secretion of thymic stromal lymphopoietin (TSLP)." (PMID 34177901, 2021).
pancreatic cancer (continued). "Thymic stromal lymphopoietin (TSLP), a key cytokine for the development of Th2 immunity, is produced by CAFs in pancreatic cancer." (PMID 32466266, 2020). "The crosstalk between CAFs and dendritic cells was also shown to affect the ability of DCs to polarize the differentiation of T cells toward a Th2 phenotype in pancreatic cancer, via CAF secretion of Thymic stromal lymphopoietin (TSLP)." (PMID 31428105, 2019). "In an in vitro study on pancreatic cancer, polarization of naïve CD4+ T cells into the Th2 subtype was promoted by a suppressive CAF phenotype upon stimulation by the thymic stromal lymphopoietin (TSLP)-dependent pathway." (PMID 40805183, 2025). "Which cells and molecules are mostly relevant in driving TSLP secretion by CAFs in pancreatic cancer is not defined." (PMID 30760333, 2019). "Additionally, in pancreatic cancer, α-SMA+ CAF-released thymic stromal lymphopoietin (TSLP) has been involved in TH2 cell polarization via myeloid DC conditioning." (PMID 31462327, 2019). "Cancer cell–produced IL-1β was previously shown to induce TSLP in breast or pancreatic cancers, but ex vivo culture of epidermis from WT mice with IL-1β did not induce TSLP production, suggesting that, at least on its own, IL-1β does not induce the expression of epidermal TSLP." (PMID 36107619, 2022). "However, although several cytokines have been reported to regulate TSLP secretion in other models, which are the most relevant inflammatory cytokines, molecules and cells involved in this regulation in pancreatic cancer is not completely elucidated." (PMID 30760333, 2019).
eosinophilic esophagitis (26 papers, 2015 to 2025). Eosinophilic esophagitis (EoE) is a chronic, allergic disease of the esophagus characterized clinically by symptoms of esophageal dysfunction (including vomiting, dysphagia, feeding disorders, food impaction and abdominal pain) which persist after treatment with proton pump inhibitors (PPIs). "The importance of TSLP is also noted in eosinophilic esophagitis, a food allergy-associated inflammatory disease, where skin-derived TSLP results in basophil-mediated disease activation in humans, which was IgE-independent (based on mice experiments)." (PMID 33333859, 2020). "Due to the finding of single nucleotide polymorphisms in genes encoding eotaxin‐3, TGF-β1, filaggrin, TSLP and TSLP receptor, a genetic susceptibility to eosinophilic esophagitis is suggested." (PMID 32601726, 2020). "In eosinophilic esophagitis (EoE), TSLP has been implicated in disease pathogenesis by activating basophils through IgE-independent mechanisms." (PMID 40443683, 2025). "A similar heterogeneity was observed in human basophils, which developed in a TSLP-elevated environment during food allergy-associated eosinophilic esophagitis (EoE)." (PMID 36846020, 2022). "In eosinophilic esophagitis (EoE), a gain-of-function polymorphism in TSLP is associated with disease in pediatric subjects, and TSLP expression was higher in esophageal biopsy samples from children with active EoE compared to subjects with inactive EoE." (PMID 40873585, 2025). "Eosinophilic esophagitis (EoE) is associated with polymorphisms in the gene encoding TSLP." (PMID 37628907, 2023). "Single Nucleotide Polymorphisms (SNPs) in both TSLP and CRLF2 coding TSLP receptor result in increased expression or signaling, and have been associated with Eosinophilic esophagitis (EoE)." (PMID 33335529, 2020). "The pathogenesis of eosinophilic esophagitis depends on local epithelial immune activation with production of eotaxin-3 and TSLP." (PMID 30778348, 2019). "This study was followed by the observation that a mouse model of eosinophilic esophagitis (EoE)-like disease was dependent on TSLP acting on basophils." (PMID 30057581, 2018). "TSLP was evaluated at both the gene and protein level, owing to its importance in Th2-mediated immune responses and eosinophilic esophagitis in particular." (PMID 29259025, 2017). "Despite growing interest in the role of alarmins, such as TSLP, IL-25, IL-33 and periostin, in allergic diseases, most existing data have been acquired from studies of adults or eosinophilic esophagitis, and little is known of their activity in children with GERD." (PMID 40981017, 2025). "The central role of the Th2 response in the pathogenesis of eosinophilic esophagitis, with the release of mediators such as thymic stromal lymphopoietin (TSLP), IL-4, IL-5, IL-13, TGFß, and eosinophil chemokines (eotaxin 1-3/CCL11-CCL24-CCL26 and RANTES/CCL5) has been demonstrated." (PMID 36902457, 2023). "Studies in eosinophilic esophagitis (EoE) have shown increased TSLP expression in esophageal tissue with basophil and mast cell infiltration, though other findings did not confirm this." (PMID 40981017, 2025). "The induction of the inflammatory form of TSLP is also observed in COPD, eczema, eosinophilic esophagitis, and inflammatory bowel disease." (PMID 33808333, 2021). "Thymic stromal lymphopoietin (TSLP), an IL-7-like cytokine, participates in several autoimmune diseases, such as eosinophilic esophagitis, inflammatory bowel disease, and rheumatoid arthritis." (PMID 33029540, 2020). "However, TSLP-activated basophils induce and perpetuate experimental eosinophilic esophagitis (EoE), which may be triggered in the absence of IgE and mast cells." (PMID 26284078, 2015).
airway hyperresponsiveness (25 papers, 2012 to 2025). "RV infection of 6 day-old mice, but not mature mice, induces type airway inflammation, mucous metaplasia and airways hyperresponsiveness which is associated with expansion of IL-13-producing ILC2s and dependent on the innate cytokines IL-25, IL-33 and TSLP." (PMID 41573550, 2025). "RV infection of 6 day-old mice, but not mature mice, induces type 2 airway inflammation, mucous metaplasia and airways hyperresponsiveness which is associated with expansion of IL-13-producing type 2 innate lymphoid cells (ILC2s) and dependent on the innate cytokines IL-25, IL-33 and TSLP." (PMID 41573550, 2025). "In clinical trials, TSLP monoclonal antibodies are effective in controlling eosinophilic inflammation in the lungs and airway hyperresponsiveness." (PMID 40443683, 2025). "We have shown that RV1B infection of 6-day-old mice induces mucous metaplasia and airway hyperresponsiveness that is associated with ILC2 expansion and dependent on IL-13, IL-25, IL-33, and TSLP." (PMID 38061015, 2024). "TSLP can stimulate the activation and proliferation of ILC2s to produce a large amount of IL-5 and IL-13, resulting in airway inflammation and airway hyperresponsiveness." (PMID 36482599, 2022). "Recent findings indicate that thymic stromal lymphopoietin (TSLP) may be a key target in airway hyperresponsiveness in allergic asthmatics." (PMID 25426119, 2014). "Tezepelumab is an IgG2 monoclonal antibody that targets thymic stromal lymphopoietin (TSLP), preventing its interaction with the heterodimeric TSLP receptor, and impacting both type-2 and non-type 2 inflammatory pathways, including allergic, eosinophilic inflammation, and airway hyperresponsiveness." (PMID 36253809, 2022). "When they gave anti-TSLP monoclonal antibody, the DEHP enhanced airway inflammation, Th2 cytokines (IL-4, IL-5 and IL-13) production, and airway hyperresponsiveness were reduced via neutralized TSLP." (PMID 37545493, 2023). "We have shown that rhinovirus A1B (RV1B) infection of 6-day-old mice, but not mature mice, induces mucous metaplasia and airway hyperresponsiveness that is associated with ILC2 expansion and dependent on IL-13, IL-25, IL-33, and TSLP." (PMID 38061015, 2024). "Several cytokines are now known to be key regulators of events that can lead to the development of airway hyperresponsiveness (AHR) and chronic inflammation, including IL-18, IL-25, IL-33 and thymic stromal lymphopoietin (TSLP), all of which are released by epithelial cells." (PMID 26214807, 2015).
eczema (23 papers, 2009 to 2025). "Eczema was associated with decreased concentrations of IFNα, IFNγ, TSLP, CXCL9, and CXCL13, but increased concentrations of CCL18 and Galectin-3." (PMID 31998285, 2019). "High levels of IL-1β, IL-17, and C-C motif chemokine ligand (CCL) 17 (TARC) and low levels of C-X-C motif chemokine ligand (CXCL) 1 and thymic stromal lymphopoietin (TSLP) in breast milk were associated with a low risk of eczema at 0–3 years of age." (PMID 31507589, 2019). "They noticed that the polymorphism of the TSLP gene, rs1898671, was associated with a reduced risk of herpetic eczema." (PMID 30304837, 2018). "In addition, eczema was associated with decreased concentrations of IFNα, IFNγ, TSLP, CXCL9, and CXCL13, but with increased concentrations of CCL18 and Galectin-3." (PMID 31998285, 2019). "Subsequent studies indicate that the coexistence of the TC and CC genotypes in the TSLP encoding gene, rs1837253, may be associated with eczema." (PMID 30304837, 2018). "Interestingly, another phthalate, di-n-butyl phthalate, up-regulated skin hypersensitivity reactions via thymic stromal lymphopoietin, a cytokine known to activate the maturation of dendritic cells and recently associated with eczema, in mice." (PMID 22732598, 2012). "This led to the identification of our lead compound BP79 which effectively abrogates TSLP-mediated effects and significantly downregulates eczema-relevant pro-inflammatory pathways and cytokines." (PMID 38877290, 2024). "Thymic stromal lymphopoietin (TSLP) is a pro-inflammatory cytokine that drives many inflammatory diseases including eczema, which has sparked great interest for therapeutic targeting." (PMID 38877290, 2024). "TSLP expression was higher in the stratum spinosum in LP, eczema, BP, PsV, and MF and higher in the stratum basale in sarcoidosis and PsV." (PMID 36046760, 2022). "In a semiquantitative analysis, TSLP was significantly expressed in the epidermis in LP, BP, eczema, PsV, sarcoidosis, and MF." (PMID 36046760, 2022). "In our study, we found elevated TSLP expression in the epidermis of eczema, BP, and MF, all of which are typical Th2-dominant dermatoses." (PMID 36046760, 2022). "The gradients of the stratum basale and the stratum spinosum expression of TSLP in sarcoidosis were different from LP (p = 0.009), eczema (p = 0.030), BP (p = 0.027), and MF (p = 0.023), respectively." (PMID 36046760, 2022). "IL4, IL13, IL1RL1, IL18R1 and TSLP are also the only proteins found to be common to eczema and rhinitis." (PMID 28598986, 2017). "Residual TSLP expression was found in mast cells, basophils and/or fibroblasts after keratinocyte-selective TSLP ablation in a VD3-induced eczema mouse model 4,12." (PMID 25866638, 2015). "(c) The immunological system of eczema focused on T helper type 2 (Th2) cell-derived cytokines, including interleukin (IL)-4 and IL-13, and keratinocyte-derived cytokines, as well as thymic stromal lymphopoietin (TSLP) and IL-33, which contribute to Th2-mediated skin inflammation in AD." (PMID 41011120, 2025). "Relevant examples of targeted pyrosequencing include hypermethylated promoter regions of the skin-related HBD-1 and inflammation-related NLRP2 genes, as well as hypomethylation of TSLP and FCERG1G genes, with the latter mediated by the TSLP over-expression in eczema individuals." (PMID 37373692, 2023). "Similarly, high levels of TSLP were observed in blister fluids of patients with BP, compared to other diseases, such as eczema, toxic epidermal necrolysis, contact dermatitis, herpes, and burn." (PMID 33029540, 2020). "Morphologically, TSLP was distinctly expressed in the epidermis of LP, BP, eczema, PsV, sarcoidosis, and MF specimens, while in the epidermis with DLE, TSLP-positive keratinocytes could also be observed focally, not as widespread as other dermatoses in our investigation." (PMID 36046760, 2022).